CD4 (CD4 molecule)
Diseases named in the same sentence as CD4 in open-access papers (continued):
Sharing a sentence is not in itself a finding about the gene and the disease.
leukemia (continued). "In our model, leukemia responsiveness correlates with in vivo CD4+ T cell activation and DC maturation, supporting a role for DC licensing." (PMID 39727041, 2025). "Although limited by our sample size, CosMx data showed potential post-ICI TWEAK signaling between leukemia cells and adjacent DC, naïve CD4 T cells, and monocyte progenitor cells." (PMID 39975227, 2025). "In this way, dendritic cells present the telomerase antigen epitopes in a MHC class I or II to CD8+ T or helper CD4+ T lymphocytes, boosting durable and specific immune responses against leukemia cells." (PMID 40563586, 2025). "In this study, we report the broad effect of BET-i on total CD4+ T cells as well as classically immunosuppressive/protumor CD4+ T cells in the leukemia microenvironment." (PMID 38775157, 2024). "Transfer of CD4+ T cells into Il21−/− AML significantly reduced leukemia burden and L-GMP numbers and frequency to levels comparable to BL/6 AML mice." (PMID 39536753, 2024). "Mice receiving ICN1-expressing Nudt1 WT cells exhibited a rapid increase in the proportion of GFP+ leukemia cells in their peripheral blood and developed overt CD4+CD8+ T-ALL within six weeks." (PMID 38493213, 2024). "This infiltration with reg CD4+ T cells has already been observed in humans, in which blood from leukemia patients contained significantly more reg CD4+ T cells than HD samples." (PMID 39518969, 2024). "The treatment effectively promoted the proliferation of CD4+T cells and the secretion of Th1 cytokines in vitro, and induced tumor-specific cytotoxic T cell responses to achieve an anti-leukemia effect." (PMID 38994350, 2024). "Conversely, APL with PML::RARA often presents with higher SSC, less expression of CD4, and more frequent overall blood cell reduction, contributing to some extent to the differentiation between the 2 leukemias." (PMID 39432585, 2024). "This megakaryocytic population later recovered at the time of AML progression, when the CD4+ T cell population contracted again, consistent with immune evasion of leukemia cells following an activated CD4+ T cell GvL response." (PMID 38884110, 2024). "Relevant literature shows that AML leukemia cells with CD4 expression originate from a relatively mature stage." (PMID 38577341, 2024). "CD70+ T-cell numbers remained higher on CD4+ subsets, and this is noteworthy given the importance of CD4+-mediated alloreactive responses as demonstrated by the tumor cell HLA class II downregulation leading to leukemia relapse." (PMID 39028952, 2024). "The substantial infiltration with reg CD4+ T cells at late stages of leukemia was an interesting finding." (PMID 39518969, 2024). "In accordance with other studies relating to leukemia, we observed that the expression levels of CD4 are a prognosis biomarker in ALL and other types of cancer." (PMID 38339034, 2024). "In our analysis, these reg CD4+ T cells highly infiltrated the spleen at the late time points after leukemia transplantation, thereby exposing the immune system of leukemic mice to immunoregulatory molecules." (PMID 39518969, 2024). "In our cohort, equal numbers of γδT-LGL leukemia cases showed the CD4−/CD8− and CD4−/CD8+ phenotypes." (PMID 39161592, 2024). "In comparison to APL with PML::RARA, APL-like AML with NPM1 mutation exhibits leukemia cells with lower SSC, frequent expression of CD4, and higher white blood cell counts." (PMID 39432585, 2024). "We addressed this question using a murine leukemia model, where we showed that leukemia elicited CD4 T cells with both a Th1-like helper and a cytotoxic phenotype." (PMID 37654482, 2023). "On Feb 2, 2022, Nature published the paper titled “Decade-long leukemia remissions with the persistence of CD4+ CAR T-cells” (Nature." (PMID 37970204, 2023). "This suggested that although the helper function of CD4 T cells was the major driver of anti-leukemia immunity, the cytotoxic function of the CD4 T cells likely still played an important role in leukemia clearance." (PMID 37654482, 2023).
leukemia (continued). "In previous our study, wt-TCR-transduced CD4+ T cells showed cytotoxicity against WT1-expressing leukemia cells in an HLA-DPB1*05:01-restricted manner." (PMID 36939853, 2023). "A combination of a targeted therapy and PDL1 blockade elicited clonal expansion of leukemia-specific helper-cytotoxic CD4 T cells, which resulted in a significant survival benefit relative to treatment with the targeted therapy or PDL1 blockade alone." (PMID 37654482, 2023). "After 1 week, unmodified or FOLR1 CAR T cells were injected into the leukemia-bearing mice at 1 × 107 cells (1:1 CD4+/CD8+ cell ratio) per mouse." (PMID 36136600, 2022). "Among the five patients with myelitis, the median age was 40 years and all patients were severely immunosuppressed (three with HIV infection and less than 500/mm3 CD4+ lymphocytes, one on immunosuppressant therapy, and one with leukemia on chemotherapy)." (PMID 35040287, 2022). "Altogether, our data suggest that CD4+ TLEX-CD8086 cells can potentially induce a stronger leukemia antigen-specific anti-leukemia CTL immune response than CD4+ TLEX-null cells and LEX-CD8086 alone." (PMID 36466863, 2022). "In the transgenic and adoptive transfer Eμ-TCL1 mouse models of CLL, Tr1-like cells were found to be essential for CD4+ T cell-mediated control of leukemia development." (PMID 35979372, 2022). "first noted increased CD4+CD25+FoxP3+CTLA-4+ Tregs occurring alongside leukemia development in the Eμ-TCL1 transgenic mouse model of CLL." (PMID 35979372, 2022). "In line with our previous observations, CD8+ CAR T cells were enriched immediately after leukemia encounter in both conditions, while CD4+ CAR T cells became prominent at later time points." (PMID 35503659, 2022). "Previous studies have found abnormal distributions of CD4+CD25+ regulatory T cells in the peripheral blood of leukemia patients, thus forming a suppressive immune microenvironment." (PMID 35504885, 2022). "Our results indicate that the phenotype of Tregs changes during the course of leukemia to establish a subpopulation of CD4+, FoxP3+, LAG-3+, CD69hi, and surprisingly, CD44lo and CD25lo cells." (PMID 35296093, 2022). "And mice treated with dTCR-T cells plus DAC showed a higher proportion of activated CD3+CD25+ cells, CD8+ cells, and CD4+ cells compared with the other groups, suggesting higher anti-leukemia activity." (PMID 36097193, 2022). "SAMHD1 downregulation on the mRNA and protein level, compared to CD4+ T-cells from healthy donors or monocytic THP-1 cells, was also observed in various CD4+ T-cell lines derived from leukemia and CTCL patients." (PMID 34480199, 2022). "We limited these experiments to the subset of CD8+ T cells as it was shown that these cells play a superior role in anti-leukemia immune response over CD4+ T lymphocytes." (PMID 35296093, 2022). "TAL1 positive leukemias frequently express CD4 and CD8 and have a cortical phenotype similar to what is observed in E2a-/- mice." (PMID 35514954, 2022). "MI-2 inhibited the progression of leukemia and increased significantly the percentage of central memory and effector CD4+ and CD8+ T lymphocytes." (PMID 35296093, 2022). "In contrast to CD8+ T cells, the role of CD4+ T cells in the control of leukemia has been studied less intensively." (PMID 36405718, 2022). "We observed that pre-treatment of leukemia cells with AZA was connected to increased Lck and Zap70 phosphorylation in CD4+ CAR T cells upon contact with the pre-treated leukemia cells." (PMID 34750374, 2021). "In CML patients, leukemia-antigen specificity of CD4+ T cells has been documented in several independent studies." (PMID 34727093, 2021). "Given that CD4+ helper T cells are also involved in eradication of IRAK1 KO leukemia cells, we also analysed the ability of MDSC to suppress CD4+ T cells." (PMID 34906138, 2021).
leukemia (continued). "Of interest, CD4+ T cells from spleens of leukemia-bearing Rag2−/− mice showed a higher frequency of TR1 cells in comparison to non-leukemic control mice, accompanied by a high co-expression of LAG3 on these cells." (PMID 33526861, 2021). "Either Il10rb+/+ (WT) or Il10rb−/− CD4+ T cells were injected into Rag2−/− mice followed by transplantation of TCL1 leukemia." (PMID 33526861, 2021). "Collectively, these data suggest a potential tumour‐suppressing role of the Th17 phenotype and IL‐23, as a cytokine that polarizes CD4+ cells towards the Th17 phenotype in leukemia and in various solid tumours." (PMID 34235838, 2021). "Whereas wild-type CD4+ T cells control TCL1 leukemia development after adoptive transfer in leukopenic Rag2−/− mice, EOMES-deficient CD4+ T cells failed to do so." (PMID 33526861, 2021). "Helenalin has been reported to cause apoptosis in various cells including renal carcinoma cells, CD4+ T cells and leukaemia cells, and to trigger necrosis in apoptosis-resistant cells such as Bcl-2 overexpressing leukaemia cells." (PMID 34959659, 2021). "WT or Eomes−/− CD4+ T cells were transplanted into Rag2−/− mice followed by adoptive transfer of TCL1 leukemia cells." (PMID 33526861, 2021). "To further examine the activation of CD4+ T-cells in the IRAK1 null leukemia model, we performed CD4 cell polarization analysis with splenocytes isolated from IRAK1 KO cell-engrafted, tumor free mice." (PMID 34906138, 2021). "It was surprising that leukemia-derived antigen was so ineffectively cross-presented, even when leukemia cell death was induced by alloreactive donor CD4 cells." (PMID 32839441, 2020). "In support of a role for CD4+ T-cells in leukemia control, we have recently shown that these cells are able to control CLL progression in the absence of CD8+ T-cells in the TCL1 AT mouse model in an Eomesodermin (Eomes)- and Il10rb-dependent manner." (PMID 32457353, 2020). "On day 21, 1 × 107 TCR DP04chim retrovirally transduced CD4 T cells were intravenously transferred into the mice and leukemia burden as well as T cell frequencies in bone marrow were analyzed seven days later (i.e., day 28)." (PMID 32443793, 2020). "Double-mutant mice show indeed an inhibition of T-cell leukemia progression, evidenced by a strong reduction of pre-leukemic CD4+CD8+ (DP) T cells in the periphery." (PMID 32346377, 2020). "Studies using the immunocompetent Eμ-TCL1 mouse model of CLL and after adoptive transfer of TCL1 leukemia (TCL1 AT) into BL/6 wild-type (WT) mice revealed more IL-4 secretion of CD4+ T-cells in comparison to control mice." (PMID 32457353, 2020). "While IL-15sol preferentially expanded CD8+ and especially CD4+ T-cells in the peritoneum, injection of IL-15Rc-secreting leukemia cells was followed by an influx and/or expansion of NK1.1+ cells in the peritoneum." (PMID 31856922, 2019). "We first evaluated the anti-leukemia activity of CD4CAR T cells in individual co-culture killing assays with three CD4-positive acute myeloid leukemia cell lines: THP-1, U937, and MOLM-13." (PMID 31413761, 2019). "WT1-siTCR/CD4+ T cells sufficiently recognized leukemia cells in an HLA class I-restricted manner and provided target-specific Th1 help for WT1-siTCR/CD8+ T cells." (PMID 30622438, 2019). "Simultaneously with PD-L1, several other markers related to AML were analyzed on leukemia blasts, and PD-1 expression was measured on T-cells gated as the CD4 or CD8-positive subset of cells in the lymphocyte gate of CD45/SSC dotplots." (PMID 31185600, 2019). "In a xenograft mouse model, it was shown that WT1-siTCR/CD4+ T cells migrate to leukemia sites and subsequently attract WT1-siTCR/CD8+ T cells via chemotaxis." (PMID 30622438, 2019). "We previously reported that the abundance of CD4+ T cells constitutively expressing PD-1 was robustly increased in lymphohematopoietic tissues during the progression of leukemia, leading to the profound immunodepression." (PMID 30603051, 2018).
leukemia (continued). "One study demonstrated that the cotransfer of CD4 + CD25+ Tregs and CD4 + CD25− effector T cells into MHC-mismatched mice with leukemia prevented GvHD while preserving the beneficial GvL effect." (PMID 30510164, 2018). "De novo, we propose that hyperactive Notch3 signaling by boosting CXCR4-dependent migration promotes anomalous egression of CD4+CD8+ cells from the thymus in early leukemia stages." (PMID 30038265, 2018). "Our series of cases included a pilot cohort of 101 T-LGL leukemia patients (68 CD8+/CD4- and 33 CD4+/CD8±) from Padua Hematology Unit (Italy) and a validation cohort of additional 20 patients from Rennes Hematology Unit (France)." (PMID 28977911, 2017). "Our results also contribute to clearly separate CD4+ from CD8+ T-LGL leukemia, the first group being characterized by very low frequency of neutropenia and lack of STAT3 mutations." (PMID 28977911, 2017). "In the CD4-HBZ transgenic mouse model, an ATL stem cell candidate (c-kit+/CD4-/CD8-) was identified and the c-kit-SCF signaling pathway was implicated in leukemia development." (PMID 29050201, 2017). "Patients with leukemia (n = 95) were estimated to have a higher long‐term CD4 concentration after HSCT than those with other conditions (P < 0.001)." (PMID 28074473, 2017). "The CD4-HBZ mice develop leukemia at older ages, around 16 months, with changes in hematopoietic profiles, splenic infiltration and systemic inflammation, as was observed in the Gzmb-HBZ mice." (PMID 29050201, 2017). "DNR-induced CD4+CD25+Foxp3+ T cells were shown to act as Tregs through the complete inhibition of leukemia-specific IFN-γ production by both CD4+ and CD8+ T cells." (PMID 29312358, 2017). "Patients who express high levels of Blimp-1 in their CD4+ T cells present with high blast counts, indicating a correlation of Blimp-1 expression to late phase leukemia development." (PMID 28629373, 2017). "Presumably, repeat interactions of host/leukemia-derived DCs and donor CD4-positive T cells are necessary for sustained GvL effects." (PMID 28638379, 2017). "Forty six phosphoramidates were prepared and biologically evaluated against three different cancer cell lines; murine leukemia (L1210), human CD4+ T-lymphocyte (CEM) and human cervical carcinoma (HeLa)." (PMID 27818111, 2016). "DMAG treatment was, however, insufficient to prolong overall survival of leukemia‐bearing mice after transplantation of allogeneic CD4+ and CD8+ T cells." (PMID 27980780, 2016). "The chemotaxis and adhesion effects on leukemia cells were ablated when CCR9 was internalized on the T-ALL CD4+ T cells, which suggests that CCR9 is closely related to the infiltration and metastasis of leukemia cells." (PMID 26879872, 2016). "Coexpression of IL-2Rα and myeloid antigen (CD13) on the leukemia cells from a representative case of IL-2Rα+CD4+AML was confirmed by double immunostaining, showing that IL-2Rα was actually expressed on AML cells, but not on T-lymphocytes." (PMID 26375984, 2015). "This indicated that tumor antigen-specific CD4+ T cells cannot be effectively activated following contact with leukemia cells." (PMID 25815463, 2015). "Gallein, a small molecule inhibitor of Gβγ, increased levels of T cell receptor (TCR)-stimulated IL-2 mRNA in primary human naïve and memory CD4+ T helper cells and in Jurkat human CD4+ leukemia T cells." (PMID 25629163, 2015). "Overall, these findings show that the expression of IDO1 in DCs matured in presence of PGE2 is able to inhibit the generation of both leukemia-reactive IFN-γ-secreting CD4+ and CD8+ T cells." (PMID 25815345, 2015). "To test the involvement of PD-1+ CD4+ T cells in the depression of the T cell immune response, we first investigated the occurrence of the PD-1+ CD4+ T cells during ageing and leukemia in mice." (PMID 24404186, 2014).
leukemia (continued). "Notably, studies in mice suggest that G-CSF may separate GVHD and graft-versus-leukemia (GVL) responses by exerting suppressive effects on CD4+ T cells, that are implicated in GVHD, while preserving the cytolytic pathways of CD8+ T cells that are critical for effective GVL." (PMID 25179788, 2014). "CLIP expression on AML blasts predicts poor clinical outcome and disturbs the activation of leukemia-specific CD4+ T cells, most probably by interfering with the loading and presentation of LAAs." (PMID 24427158, 2013). "The Fli-1 leukaemia phenotype was very similar to the preleukaemic phenotype with reduced CD4+, CD4+8+ and expanded CD8+ cells evident." (PMID 23667468, 2013). "Adult T-cell leukemia (ATL) is a leukemia derived from mature CD4+ T cells and induced by human T-cell leukemia virus type 1 (HTLV-1) infection." (PMID 23198153, 2012). "Here, we characterized the effects of nilotinib for the first time on CD4+CD25+ regulatory T cells (Tregs) which regulate anti-tumor/leukemia immune responses." (PMID 20113470, 2010). "As a model for activated CD4+ T cells, we used Jurkat T cells, a cell line derived from a human leukemia that has been widely used in T cell activation studies." (PMID 18773076, 2008). "In accordance with this, DCs loaded with apoptotic leukaemia cells stimulated both CD4+ and CD8 positive T cells and mRNA loaded DCs were superior in inducing CD8+ T-cell responses." (PMID 15720715, 2005). "We have compared DCs either loaded with apoptotic leukemia cells or transfected with mRNA from the same leukemia cell line, Jurkat E6, for their capacity to induce specific CD4+ and CD8+ T-cell responses." (PMID 15720715, 2005). "The leukemia microenvironment associated with this signature showed enrichment of non-exhausted CD4+ and CD8+ T cytotoxic lymphocytes and expansion of CD8+ T effector memory cells re-expressing CD45RA (TEMRA) in patients with a favorable prognosis." (PMID 42122217, 2026). "Despite the predominance of Th2/Th10-biased CD4+ iNK T cells, which are traditionally associated with lower cytotoxic potential, CB-8F4CAR-iNK T cells demonstrated non-inferiorlysis of leukemia targets compared to adult-derived counterparts." (PMID 40519924, 2025). "Also, CD57+ CD4 T cells were shown to exhibit significant cytotoxic activity against leukemia cells." (PMID 40868094, 2025). "In addition to the lysis of leukemia cells by cytotoxic T lymphocytes, the hTERT epitope can be recognized by antigen-presenting cells, thereby boosting either the promotion of helper CD4+ T cells or cytotoxic CD8+ T cell responses." (PMID 40563586, 2025). "However, despite the increase in T cells, the anti-leukemia immune response is impaired due to multiple immune escape mechanisms, such as the predominant expansion of Tregs among CD4+ T cells." (PMID 40861464, 2025). "The authors concluded that although the initial response to CAR-T therapy is predominantly mediated by the CD8+ and double negative (CD4-CD8-Helioshi) population, at later time points a distinct population of CD4+ CAR-T cells is responsible for cytotoxicity against leukemia cells." (PMID 38455066, 2024). "Additionally, CMV-R can impact the reconstitution of leukemia-specific T cells and the expansion of specific CD4+ T cell subsets, potentially contributing to the GVL effect and immune protection against pathogens." (PMID 39655058, 2024). "In addition, multiple studies showed that reg CD4+ T cells contribute to leukemia progression by establishing an immune-privileged niche benefiting the proliferation of leukemia stem cells (LSCs) by protecting them from elimination via CD8+ T cells." (PMID 39518969, 2024). "In addition, increased CD4+CD25+FOXP3+CTLA-4+ Tregs occurring alongside leukemia development were described in the Eμ-TCL1 transgenic mouse model of CLL." (PMID 39335199, 2024).